GAB2 (GRB2 associated binding protein 2)
Description:
Adapter protein which acts downstream of several membrane receptors including cytokine, antigen, hormone, cell matrix and growth factor receptors to regulate multiple signaling pathways. Regulates osteoclast differentiation mediating the TNFRSF11A/RANK signaling. In allergic response, it plays a role in mast cells activation and degranulation through PI-3-kinase regulation. Also involved in the regulation of cell proliferation and hematopoiesis.
Synonyms: KIAA0571
Tractability: Small molecule: a structure with a bound ligand is known. Antibody: UniProt places it where antibodies can reach, with high confidence; its Gene Ontology location is reachable by antibodies, with high confidence; the Human Protein Atlas places it where antibodies can reach. PROTAC: its protein half-life has been measured.
Gene: Protein-coding gene on chromosome 11 (78,215,293 to 78,418,348, reverse strand). Ensembl gene ENSG00000033327.
Subcellular location: Cytoplasm; Cell membrane; Membrane raft
Subcellular location (Human Protein Atlas): Plasma membrane
Pathways (Reactome):
Immune System: FLT3 Signaling; Interleukin receptor SHC signaling; Interleukin-15 signaling; Role of LAT2/NTAL/LAB on calcium mobilization; STAT5 Activation; Signaling by CSF1 (M-CSF) in myeloid cells; Signaling by CSF3 (G-CSF)
Disease: Constitutive Signaling by Aberrant PI3K in Cancer; STAT5 activation downstream of FLT3 ITD mutants; Signaling by FLT3 ITD and TKD mutants; Signaling by FLT3 fusion proteins; Signaling by cytosolic FGFR1 fusion mutants
Signal Transduction: PI3K Cascade; PI5P, PP2A and IER3 Regulate PI3K/AKT Signaling; PIP3 activates AKT signaling; Signaling by SCF-KIT
Developmental Biology: RET signaling
Gene Ontology:
Molecular function: protein binding; transmembrane receptor protein tyrosine kinase adaptor activity; phosphatidylinositol-3,4,5-trisphosphate binding; phosphatidylinositol-3,4-bisphosphate binding
Biological process: osteoclast differentiation; positive regulation of cell population proliferation; phosphatidylinositol 3-kinase/protein kinase B signal transduction; positive regulation of mast cell degranulation; signal transduction; cell surface receptor protein tyrosine kinase signaling pathway
Cellular component: cytoplasm; plasma membrane; cytosol; membrane raft
Genetic constraint (gnomAD): Loss-of-function variants: 20 observed, 52.04 expected, observed/expected ratio (o/e) 0.38, 90% interval 0.27 to 0.56. The upper end of that interval is the gene's LOEUF score, 0.56, which puts it in group 2 of 6, group 1 being the genes least tolerant of losing a copy. Missense variants: 774 observed, 810.99 expected, observed/expected ratio (o/e) 0.95, 90% interval 0.9 to 1.01. Synonymous variants: 295 observed, 311.81 expected, observed/expected ratio (o/e) 0.95, 90% interval 0.86 to 1.04.
Homologues: Orthologues: chimpanzee GAB2 (99% identical), macaque GAB2 (99% identical), pig GAB2 (94% identical), rabbit GAB2 (94% identical), mouse Gab2 (92% identical), dog GAB2 (89% identical), rat Gab2 (89% identical), guinea pig GAB2 (88% identical), tropical clawed frog gab2 (73% identical), zebrafish gab2 (64% identical), Drosophila melanogaster dos (22% identical), Caenorhabditis elegans soc-1 (13% identical). Paralogues in human: GAB4 (50% identical), GAB1 (41% identical), GAB3 (32% identical), PHLDB1 (22% identical), PHLDB2 (15% identical), PLEKHS1 (12% identical), PHLDB3 (6% identical).
Diseases named in the same sentence as GAB2 in open-access papers:
GAB2 is named in the same sentence as 100 diseases in open-access papers, as found by Europe PMC text mining. Sharing a sentence is not in itself a finding about the gene and the disease. The quoted sentences say what the papers report.
melanoma (31 papers, 2009 to 2025). A malignant, usually aggressive tumor composed of atypical, neoplastic melanocytes. "Melanomas with BRAF class 1 mutations harbored fewer amplifications of GAB2 (FDR = 0.099), CCND1, and PAK1 (both FDR = 0.18)." (PMID 35706047, 2022). "Except for GAB2 mutation, GAB2 amplification or overexpression has been detected in ovarian, lung, breast cancers and melanoma." (PMID 34419139, 2021). "Gab2 is also associated with tumor behavior in other types of malignancies, such as breast cancer, melanoma, ovarian cancer, lung cancer, glioma, and gastric cancer." (PMID 28842424, 2017). "Gab2 amplification is associated with melanoma arising from sun-protected sites and often occurs independently from oncogenic NRAS or BRAF mutations or amplifications of the KIT gene." (PMID 26095858, 2015). "It has been previously reported that aberrant Gab2 and/or Gab2 signaling is closely associated with human tumorigenesis, particularly in breast cancer, leukemia and melanoma." (PMID 26095858, 2015). "Finally, SPRY2 (Bladder), CBL (Endometrial), TGFA (Melanoma) and GAB2 (Non-small cell lung) genes have high risk rate and low survival rate." (PMID 34764329, 2021). "The most recurrently affected TAD boundary in both acral (n = 27; 23%) and mucosal (n = 7; 11%) melanomas was chr11:77750000–77825000, which is adjacent to TADs containing the cancer genes GAB2 and PAK1." (PMID 38758740, 2024). "GAB2 amplification is critical for melanomas arising from sun-protected sites and in mast cell development GAB2 is required for KitL/c-Kit signalling which is an important signal in melanogenesis." (PMID 37389979, 2023). "After Survival Analysis we concluded that four genes (SPRY2-for Bladder cancer, CBL-for Endometrial cancer, TGFA-for Melanoma and GAB2 for Non-small cell lung cancer) were the Biomarkers for Nitroglycerin." (PMID 34764329, 2021). "Consistent with our findings, Gab2 was reported to be an inducer of tumor angiogenesis essential for melanoma and ovarian cancer." (PMID 28420432, 2017). "Forced expression of Gab2 can promote the proliferation and invasion of melanoma and breast cancer cells." (PMID 28842424, 2017). "For example, Gab2 induces tumor angiogenesis in NRAS-driven melanoma through the RAS/ERK signaling to upregulate hypoxia inducible factor-1a (HIF-1a)." (PMID 28420432, 2017). "In melanoma, Gab2 expression promotes the migration, invasion and metastasis of tumor cells via activation of the PI3K/AKT signaling." (PMID 26754532, 2016). "In accordance with our study, Gab2 was reported to be one of the molecules essential for both ovarian cancer and melanoma." (PMID 26754532, 2016). "Pharmacologic activation of the PI3K-pathway by inhibition of PTEN leads to increased wound healing in corneal epithelial cells and it is essential for the Gab2-mediated migration of ovarian cancer cells and melanoma cells." (PMID 26824610, 2016). "Metastatic melanomas express significantly higher levels of Gab2, compared with primary melanomas and melanocytic nevi, identifying Gab2 as a molecular marker for neoplastic progression." (PMID 26095858, 2015). "Compared with its role in breast cancer and melanoma, the function of Gab2 in ovarian carcinoma is less well understood." (PMID 26095858, 2015). "Many of these genes have previously been implicated in melanoma metastasis and prognosis prediction, including MYC, GPNMB, GAB2, and SATB1." (PMID 25116415, 2014). "Gab2 has also been found to be amplified and overexpressed in melanoma, more so in metastatic than primary melanoma." (PMID 23805312, 2013). "During progression of melanoma, expression of the scaffolding and adaptor protein Gab2 is often found to be amplified." (PMID 21887372, 2011). "The highest GAB2 alteration frequency occurred in melanoma, followed by OV, NSCLC, BRCA and BLCA." (PMID 38995439, 2024).
melanoma (continued). "GAB2 was expressed at higher levels in metastatic melanoma than in primary melanoma, and it could enhance the invasiveness of melanoma cells by inhibiting the PI3K-Akt pathway." (PMID 35116193, 2022). "DEG analysis further revealed upregulation of genes SPRY2 (Bladder), and GAB2 (Non-small cell lung) and downregulation of genes CBL (Endometrial), TGFA (Melanoma) were associated with low survival rate and high risk of death as measured by survival probability and AUC score." (PMID 34764329, 2021). "Increased Gab2 DNA copy number and gene amplification are present in a subset of melanoma samples." (PMID 28842424, 2017). "GAB2 encodes a member of the GRB2-associated binding protein (GAB) gene family and is associated with human tumorigenesis, particularly in breast cancer, leukemia and melanoma." (PMID 29207374, 2017). "GAB2 is known to be overexpressed in multiple human tumors especially in melanoma." (PMID 27993151, 2016). "Grb2-associated binder 2 (Gab2), a member of the DOS/Gab family of scaffolding adapters, has been reported to play important roles in the progression and metastasis of human cancers, particularly in breast and ovarian cancers and melanoma." (PMID 26754532, 2016). "However, Gab2 is co-expressed with NRAS in melanoma cell lines and tumor samples, and its expression correlates with metastatic potential." (PMID 26095858, 2015). "GAB2 plays a prominent role in leukemia, breast and ovarian cancer and melanoma." (PMID 24349524, 2013). "The presence of Gab2 aggravates the invasiveness and mestastatic capabilities of melanoma." (PMID 21887372, 2011). "Thus, Gab2 and Grb2 signaling in melanoma cells does enhance oncogenic phenotype; These Gab2-dependent phenotypes are reported to be mediated via the PI3 kinase-Akt signaling pathway." (PMID 21887372, 2011). "Lastly, as Gab2 is an important amplifier of PI3K signalling, it is tempting to speculate that Gab2 overexpression might cooperate with the BRAFV600E oncogene in melanoma." (PMID 19737390, 2009). "Importantly, knockdown and over-expression experiments revealed that Gab2 enhances the migratory and invasive behaviour of melanoma cells in a PI3K-dependent manner." (PMID 19737390, 2009). "In acral melanoma with an amplified 11q13-14 region, investigators were able to identify the presence of 11q13-14 amplification in nearby melanoma in situ lesions in almost every case, suggesting that GAB2 overexpression may also play an early, facilitating role in these tumors." (PMID 40773291, 2025). "Furthermore, Gab2 governs tumorigenic signaling and is a novel potential therapeutic target in leukemia, breast cancer, ovarian cancer, and melanoma; therefore, we hypothesized that Gab2 may be involved in hepatocellular carcinogenesis." (PMID 28842424, 2017). "While several studies indicated that GAB2 was associated with tumor metastasis in breast cancer, colorectal cancer, melanoma, and ovarian cancer, our study failed to reveal a significant relationship between GAB2 expression and lymph node metastasis in PDAC patients." (PMID 28558797, 2017). "In contrast to the over-expression of Gab2 in metastatic melanoma, normal human melanocyte lines, melanocytic nevi and primary melanomas displayed low Gab2 expression levels suggesting that Gab2 overexpression might represent a marker of neoplastic progression." (PMID 19737390, 2009). "To explore the potential of BRD4, GAB2, and IRS2 as therapeutic targets for melanoma brain metastasis, we evaluated the anti‐melanoma functions of small‐molecule inhibitors of these proteins." (PMID 40285526, 2025). "successfully created several zebrafish ‘Fin’ melanoma systems that are driven by genes such as CRKL, GAB2 and NF1, analogous to human melanomas that lack BRAF/KIT/NRAS alterations." (PMID 39627834, 2024). "Among these hub genes, GAB2 is an adaptor protein commonly overexpressed in melanoma that upregulates RAS-ERK and PI3K-AKT pathways and promotes melanoma metastasis." (PMID 32831131, 2020).
melanoma (continued). "Gab2 can recruit Shp2 to activate Ras/ERK signaling in breast cancer and melanoma, and the PI3K/Akt signaling pathway has been reported to be modulated by Gab2 in breast cancer, ovarian cancer, and melanoma." (PMID 28842424, 2017). "GAB2, found to be amplified in 30.6% of acral melanomas and 17.1% of mucosal melanomas, has been shown to induce tumour angiogenesis by regulating hypoxia inducible factor 1 subunit alpha (HIF‐1α) and VEGF expressions in NRAS‐driven melanoma." (PMID 39757723, 2025). "Similarly, GAB2 is involved in the activation of the MAPK and PI3K/AKT pathways, and has been proposed to play a role in angiogenesis in melanomas." (PMID 38758740, 2024). "PAK1 and GAB2 were well known regulators of the MAPK pathway and might participate in the regulation of melanoma development and response to therapies." (PMID 35844619, 2022). "GAB2 CNV gains have also been reported in non-sun-damaged melanoma, including AMs and MUs, and have been reported to be mutually exclusive of BRAF, NRAS, and KIT aberrations." (PMID 33826614, 2021). "Moreover, Gab2 contributes to the angiogenic switch by increasing hypoxia-inducible factor-1α and VEGF levels in melanoma." (PMID 28842424, 2017). "Furthermore, Gab2 promotes tumor cell migration and invasion by activating PI3K/AKT signaling, and enhances tumor growth and metastasis in vivo, suggesting a role for Gab2-mediated signaling in promoting metastatic capability in melanoma." (PMID 26095858, 2015). "Although, Gab2 might not be important in melanocytes it has been shown that Gab2 knock down melanoma cells exhibit decreased migration and invasion capabilities." (PMID 21887372, 2011).
breast carcinoma (28 papers, 2009 to 2025). "GAB2 also seems to collaborate with other oncogenes linked to the progression of breast cancer, including the SRC family." (PMID 34764329, 2021). "By inhibiting let-7g, breast cancer cell migration and invasion were promoted via the downregulation of Grb2-associated binding protein 2 (GAB2) and fibronectin 1 (FN1) expressions that led to subsequent activation of MAPK pathways." (PMID 30959863, 2019). "This indicates that a variety of RTKs implicated in breast cancer development or progression use Gab2 to amplify their signals." (PMID 19737390, 2009). "Similarly, another study indicated that the level of Gab2 expression was significantly associated with metastatic progression of breast cancer." (PMID 26754532, 2016). "An important avenue for further research will be to identify whether Gab2 associates with patient prognosis or therapeutic responsiveness in particular malignancies, such as breast cancer." (PMID 19737390, 2009). "In other malignancies, recurrent amplification of 11q14.1 (containing GAB2) has been identified in breast cancer (24.7% of patients), ovarian cancer (44% of patients), and acral melanoma (47% of patients)." (PMID 40773291, 2025). "Researches have shown that GAB2 highly expressed in breast cancer, colorectal cancer, bladder cancer, osteosarcoma, ovarian cancer and other tumors." (PMID 38995439, 2024). "Recent studies have found that GAB2 was highly expressed in breast cancer, ovarian cancer, lung cancer, glioma and other malignant tumors, and was involved in regulating the occurrence and metastasis of tumors." (PMID 38995439, 2024). "In breast cancer, miR-98-5p and miR-125A-5p target Gab2 to suppress cell growth and invasion but induce cell apoptosis." (PMID 36421826, 2022). "Multiple miRNAs suppress Gab2 transcription in many types of cancer, such as breast cancer, colorectal cancer, glioma cells, and renal cell cancer cells, thus inhibiting the growth and metastasis of cancer cells." (PMID 36421826, 2022). "Gab2 is active in a variety of cancers, such as breast cancer, ovarian cancer, lung cancer, leukemia, melanoma, and glioma, and it is considered a potential oncogene." (PMID 36421826, 2022). "MiR-125a-5p has been reported to inhibit the expression of GAB2 and Bax proteins, and ultimately inhibited the proliferation and invasion of breast cancer cells." (PMID 32536819, 2020). "GAB2 encodes the GRB2 associated binding protein 246 and has been studied in breast cancer, ovarian cancer, hepatocellular carcinoma, lung cancer, and melanoma." (PMID 31974418, 2020). "Leptin upregulation of VEGF/VEGFR-2 is mediated by leptin-induced JAK/STAT3-Notch expression while also showing that leptin regulation of VEGF/VEGFR2 in breast cancer involves the activation of Src and Gbr2/Gab2/STAT3, suggesting crosstalk with Rho-GTPases." (PMID 27472371, 2016). "Although the mechanisms by which Gab2 contribute to breast cancer remain to be fully elucidated, the recruitment of SHP2 and subsequent activation of the RAS/MAPK pathway are reported to be required." (PMID 26095858, 2015). "Gab2 and ErbB2 are co-amplified in a subset of breast carcinoma, and co-expression of Gab2 with ErbB2 results in an invasive phenotype, and increases proliferation of MCF-10A mammary cells in a three-dimensional culture." (PMID 26095858, 2015). "By contrast, ablation of Gab2 in several breast cancer cell lines, inhibiting genomic amplifications, leads to a decrease in proliferation, due to a reduction in cell-cycle progression and increased apoptosis, and a reduction in their invasive potential." (PMID 26095858, 2015). "The Shp2 expression pattern is correlated with that of the estrogen receptors (ERs) in breast tumors, and the expression of Gab2, a pattern protein of Shp2, is induced by E2 in breast cancer cells." (PMID 25048202, 2014).